APOC1 (apolipoprotein C1)
Diseases named in the same sentence as APOC1 in open-access papers (continued):
Sharing a sentence is not in itself a finding about the gene and the disease.
glioblastoma (10 papers, 2019 to 2025). The most malignant astrocytic tumor (WHO grade IV). "First, the TCGA database was used to analyze the expression level of APOC1 and its association with prognosis in glioblastoma patients." (PMID 37981873, 2023). "This study revealed the role of APOC1 in promoting glioblastoma malignancy and the potential underlying molecular mechanism." (PMID 37981873, 2023). "From a practitioner’s point of view, the use of serum ApoC1 levels as glioblastoma biomarker with an impact on clinical or diagnostic decision-making seems out of reach." (PMID 36216850, 2022). "The study demonstrates the expression of ApoC1 in glioblastoma cells, with detection of mRNA in tissue, positive immunostaining in slides and two protein peaks corresponding to the sizes of ApoC1 splice variants in glioblastoma cyst fluid." (PMID 31006040, 2019). "Apolipoprotein C1 promotes glioblastoma development by inhibiting ferroptosis through reduced CBS activity and increased GSH synthesis." (PMID 40165005, 2025). "In glioblastoma cells with high expression of apolipoprotein C1, the expression of CBS can be increased, which can stimulate the transsulfuration pathway, increase GSH synthesis, and induce ferroptosis resistance." (PMID 41154707, 2025). "Previous studies have indicated that APOC1 serves as a prognostic marker for cervical cancer, ovarian cancer, and liver cancer, and it promotes glioblastoma tumorigenesis by inhibiting ferroptosis regulated by the KEAP1/NRF2 and CBS." (PMID 39877420, 2024). "Meanwhile, miR-660-3p can partially nullified the oncogenic effect of the APOC1 on glioblastoma cells." (PMID 37981873, 2023). "Glioblastoma cells (U87 and U251) transfected with miR-660-3p mimic showed a significant reduction of APOC1 mRNA and protein." (PMID 37981873, 2023). "APOC1 was overexpressed in glioblastoma compared with normal peritumoral tissue and was inversely related to patient prognosis." (PMID 37981873, 2023). "In order to clarify the expression of APOC1 in glioblastoma, we detected the APOC1 protein expression level in U87, U251 and HEB cells." (PMID 37981873, 2023). "Two glioblastoma cell lines (U87 and U251) were used to explore the role of APOC1 and its upstream miRNA-660-3p in glioblastoma tumorigenesis in vitro." (PMID 37981873, 2023). "In this study, two glioblastoma cell lines (U87 and U251) were used to explore the role of APOC1 and miRNAs in glioblastoma tumorigenicity." (PMID 37981873, 2023). "To explore the potential molecular mechanism by which APOC1 promotes glioblastoma malignancy, we examined some common tumor signaling pathways after the APOC1 was knocked down." (PMID 37981873, 2023). "Mechanistically, APOC1 drives the malignancy of glioblastoma by activating the TGFβ2 signaling pathway." (PMID 37981873, 2023). "Third, miRNA targeting APOC1 was identified, and its role in glioblastoma malignancy in vitro was assessed by transfecting cells with its mimic or inhibitor." (PMID 37981873, 2023). "Our study reveals that miRNA-660-3p inhibits the glioblastoma tumorigenesis by targeting the APOC1-TGFβ2 signaling pathway." (PMID 37981873, 2023). "Glioblastoma U87 and U251 cells with stably APOC1 knocked down (lv-shAPOC1) were constructed by transfecting lentivirus." (PMID 37981873, 2023). "Glioblastoma cells (U87 and U251) transfected with APOC1 plasmid (pAPOC1) showed upregulated APOC1 mRNA and protein, increased cell proliferation, and enhanced cell migration and invasion." (PMID 37981873, 2023). "A correlation of these values to tumor volume or the clinical course of the patients would then eventually allow the use of ApoC1 as serum biomarker for glioblastoma." (PMID 36216850, 2022). "As a most interesting result, the mean postoperative ApoC1 values in the whole cohort and in the subset of 70 glioblastoma patients were significantly lower than the mean preoperative values and the mean levels obtained during chemotherapy." (PMID 36101402, 2022).
glioblastoma (continued). "In the present cohort, a significant decrease of mean ApoC1 serum levels was detected after glioblastoma resection." (PMID 36216850, 2022). "Apolipoprotein C1 (ApoC1) has been detected immunohistochemically in glioblastoma tissue, probably expressed by activated monocytes and microglia." (PMID 36216850, 2022). "Of note, the ApoC1 levels of glioblastoma patients fell significantly after the neurosurgical resection of the tumor and then rose again during chemotherapy." (PMID 36101402, 2022). "Concerning the first neurosurgical intervention for glioblastoma, the mean preoperative ApoC1 serum level was significantly higher than the mean postoperative value." (PMID 36216850, 2022). "In the 176 glioblastoma samples, the mean ApoC1 level was 130.0 μg/mL (median 86.23, SD 314.9), which was neither different from the whole group nor from patients with spinal interventions (215.1 μg/mL, median 63.6, SD 404.9)." (PMID 36101402, 2022). "In the examined patients, ApoC1 serum levels fell significantly after neurosurgical resection of glioblastoma." (PMID 36216850, 2022). "Since up to 40% of glioblastoma tissue consist of activated monocytes or microglia, detectable amounts of ApoC1 in glioblastoma samples can occur." (PMID 36216850, 2022). "Suppression of toll-like receptor dependent activation of microglia by ApoC1 has been observed, hypothetically constituting an autocrine loop for modulation of immune response or even enabling an immune escape of glioblastoma cells." (PMID 36216850, 2022). "Therefore, miRNA-660-3p/APOC1 axis can serve as potential intervention targets in managing glioblastoma progression." (PMID 37981873, 2023). "APOC1 expression is negatively correlated to glioblastoma prognosis." (PMID 37981873, 2023). "However, there has not been any study exploring the potential relationship between miRNAs and APOC1 in glioblastoma tumorigenicity." (PMID 37981873, 2023). "Our findings suggest that miR-660-3p/APOC1/TGFβ2 axis may serve as a new potential therapeutic target for glioblastoma." (PMID 37981873, 2023). "In conclusion, the miRNA-660-3p-APOC1 axis could inhibit the glioblastoma malignancy by negatively regulating the TGFβ2 signaling pathway." (PMID 37981873, 2023). "The expression of APOC1 was much higher in glioblastoma than in normal paraneoplastic tissue." (PMID 37981873, 2023). "APOC1 suppression through shRNA or miRNA-660-3p could lead to reduced cell proliferation, migration, and invasion in glioblastoma cells and reduced tumor growth in tumor xenografts." (PMID 37981873, 2023). "Further, we discovered that APOC1 inhibition downregulates TGFβ2 and disrupts its associated downstream SMAD3 and pSMAD3, revealing a new signaling pathway involving the miR-660-3p/APOC1/TGFβ2 axis in the development of glioblastoma." (PMID 37981873, 2023). "The present study was conceived to determine whether the amount of intratumoral ApoC1 expression leads to measurable changes of serum levels after glioblastoma resection or during recurrence." (PMID 36216850, 2022). "Ongoing research deals with a detailed statistical analysis to determine whether ApoC1 serum levels qualify for use as a blood biomarker for glioblastoma." (PMID 36101402, 2022). "When comparing these values to the results from the literature, it remains questionable whether the glioblastoma-derived ApoC1 synthesis overrides the levels obtained by physiologic production in the liver or postprandial hyperlipoproteinemia." (PMID 36216850, 2022). "A detailed statistical analysis of individual ApoC1 values, histological diagnoses, treatment course, and survival time will be mandatory to answer the question of whether ApoC1 serum levels qualify as a biomarker for glioblastoma." (PMID 36101402, 2022). "The present study shows the presence of ApoC1 and LuzP6 in glioblastoma cells." (PMID 31006040, 2019).
glioblastoma (continued). "Furthermore, the Kaplan-Meier curves from TCGA database revealed a lower survival rate in glioblastoma patients with high APOC1 expression, suggesting that APOC1 may serve as a potential pro-oncogene in the development of glioblastoma." (PMID 37981873, 2023). "This study showed that APOC1 is significantly elevated in human glioblastoma tissues, and its inhibition led to decreased cell proliferation, migration, and invasion in vitro and tumor growth in vivo, suggesting that APOC1 may serve as a driver gene in glioblastoma malignancy." (PMID 37981873, 2023). "Targeting APOC1 or miRNA-660-3p may provide a new therapeutic intervention for glioblastoma." (PMID 37981873, 2023). "Consequently, higher ApoC1 expression could correspond to larger glioblastoma volume or recurrent growth of tumor cells." (PMID 36216850, 2022). "Although pathophysiologically of interest, ApoC1 serum levels did not qualify as a potential biomarker in glioblastoma management." (PMID 36216850, 2022). "Single absolute serum levels of ApoC1 do not allow an estimation of glioblastoma activity or tumor response." (PMID 36216850, 2022). "Thus, a single absolute ApoC1 serum value does not allow conclusions concerning the activity of the glioblastoma." (PMID 36216850, 2022). "However, the role of APOC1 and its upstream miRNA has not been explored in glioblastoma." (PMID 37981873, 2023). "However, the lack of correlation of ApoC1 serum values to tumor volume on MRI and to protein expression in histological slides, as well as the missing relationship of ApoC1 levels to survival time do not favor the use of ApoC1 as serum biomarker or prognostic marker for glioblastoma." (PMID 36216850, 2022).
hepatocellular carcinoma (10 papers, 2022 to 2025). A malignant tumor that arises from hepatocytes. "Besides, APOC1+ macrophages were reported as tumor-associated macrophages in hepatocellular carcinoma (HCC)." (PMID 37380987, 2023). "Genes associated with lipid metabolism, such as APOA2, APOC3, APOC1, and APOE, were significantly upregulated in multiple cell types of hepatocellular carcinoma, indicating enhanced lipid metabolic activities." (PMID 39944086, 2025). "Furthermore, in hepatocellular carcinoma (HCC), single-cell RNA sequencing has unearthed the pivotal role of APOC1 in modulating the tumor-associated macrophage (TAM) phenotypes from pro-tumor M2 to pro-inflammatory M1 through the ferroptosis pathway." (PMID 39150660, 2025). "For instance, inhibition of APOC1 can increase the M1/M2 macrophage ratio through regulating ferroptosis and improve the anti-PD-1 immunotherapy efficacy for hepatocellular carcinoma (HCC)." (PMID 37388742, 2023).
hypertriglyceridemia (10 papers, 2018 to 2024). A laboratory test result indicating elevated triglyceride concentration in the blood. "Inhibition of the apoE-mediated hepatic uptake of VLDL is not the sole mechanism accounting for the hypertriglyceridemic effect of apoC1 overexpression since apoC1 transgenic mice also develop hypertriglyceridemia in an apoE-deficient context." (PMID 36471375, 2022). "Hypertriglyceridemia or mixed hyperlipidemia, were also associated with alterations in the distribution of apoC1 between lipoproteins, i.e. an enrichment in VLDL at the expense of HDL." (PMID 36471375, 2022). "When hypertriglyceridemia was induced by a fructose administration, the decrease in plasma ApoC1 caused by hepatic deletion of SHP was associated with increased lipase activity and faster TG clearance in SHPΔhep mice than in SHPfl/fl mice." (PMID 34065318, 2021). "In hyperlipidemic individuals, several groups reported increased plasma levels of apoC1, especially in the context of hypertriglyceridemia or mixed hyperlipidemia, with values reaching 200 mg/L in some studies." (PMID 36471375, 2022). "This relative enrichment of VLDL during hypertriglyceridemia has been proposed to result from 1) increased hepatic apoC1 production coupled with enhanced VLDL secretion and/or 2) redistribution from HDL to VLDL in the circulation since apoC1 has been demonstrated to be a highly exchangeable protein." (PMID 36471375, 2022). "Transgenic mice of ApoC1 have impaired plasma TG clearance and severe hypertriglyceridemia." (PMID 34065318, 2021).
Insulin resistance (10 papers, 2016 to 2025). Increased resistance towards insulin, that is, diminished effectiveness of insulin in reducing blood glucose levels. "Furthermore, investigations in mice overexpressing Apoc1 have shown that Apoc1 is linked to liver fibrosis and insulin resistance." (PMID 36242090, 2022). "Since patients with PCOS are more obese and have a more severe insulin resistance compared with the controls in this study, it is possible that the effects of apoC1 genetic variations on metabolic profile may be disturbed or weakened by these factors in patients." (PMID 29636060, 2018). "In addition, there is marked APOC1 elevation in women with PCOS; however it is unclear how much of the altered lipid metabolism is due to estrogen and/or androgen metabolism or because of insulin resistance." (PMID 40182431, 2025).
cognitive decline (9 papers, 2022 to 2025). "AD patients carrying the APOC1 risk allele have been reported to experience faster cognitive decline and an earlier conversion from MCI to AD when they also carry the APOE ε4." (PMID 40369256, 2025). "APOC1 variants and the ε4 allele may contribute synergistically to cognitive decline and AD pathogenesis." (PMID 36330582, 2022). "We analyzed the spatial correlation between APOC1 expression and cortical atrophy and probed the potential link between APOC1 levels and accelerated conversion to AD and cognitive decline." (PMID 40369256, 2025). "Multiple studies have confirmed that APOC1 is involved in amyloid-β (Aβ) accumulation and contributes to cognitive decline and memory impairment, similar to the effects observed with APOE ε4." (PMID 40369256, 2025). "Additional research is needed to elucidate the mechanisms by which ApoC1 interacts with systemic inflammation and its role in cognitive decline." (PMID 41294487, 2025). "Our study confirmed a significant role of APOC1 expression in accelerating CTh changes during the conversion from MCI to AD, which was further related to memory loss and cognitive decline." (PMID 40369256, 2025). "Evidences have also suggested that APOEε4 itself increases cognitive decline, and APOC1 H2 has a synergistic effect with APOEε4 in increasing the risk of cognitive decline." (PMID 35839250, 2022). "APOC1 influences AD development through its role in cholesterol metabolism, with the APOC1 H2 allele potentially acting synergistically with APOE to increase the risk of cognitive decline." (PMID 40557283, 2025). "Finally, the impact of APOC1 expression on cognitive decline was mediated by cortical atrophy." (PMID 40369256, 2025). "The co-presence of APOE ε4 and APOC1 risk alleles has been reported to be more strongly associated with AD than APOE ε4 alone, indicating that the interaction between these two genes may contribute to the development of AD and cognitive decline." (PMID 40369256, 2025).
diabetic nephropathy (9 papers, 2010 to 2024). "Our findings highlighted that HOXD9/APOC1 was a key player in causing podocyte injury in diabetic kidney disease and led to macrophage M1 polarization through the NF-κB signaling pathway." (PMID 39511608, 2024). "Given that APOC1 plays a pivotal role in mediating inflammatory responses and in light of diabetic kidney disease being intricately associated with inflammation, the salience of APOC1 in the progression of diabetic kidney disease is made apparent." (PMID 39511608, 2024). "A meta-analysis reported an association between a polymorphism of apoC1 (rs4420638) and the risk of developing diabetic nephropathy." (PMID 36471375, 2022). "Our research indicates that APOC1 might be a novel diagnostic biomarker for diabetic nephropathy for the first time and suggest that APOC1 may be available as a candidate intervention target for DN." (PMID 36891052, 2023). "The results revealed that protein expression of APOC1 was increased in patients with diabetic kidney disease." (PMID 39511608, 2024). "In vivo, we also demonstrated that APOC1 expression was significantly increased in diabetic nephropathy kidney tissues, mainly in the glomerulus, using a mouse model of diabetic nephropathy." (PMID 36891052, 2023). "APOC1 expression is elevated in patients with diabetic nephropathy through multiple cohorts of the experimental GEO database (GSE96804, GSE47185, GSE30122, and the ERCB Nephrotic Syndrome Tublnt cohorts in Nephroseq database)." (PMID 36891052, 2023). "Yet, in the same experimental model, overexpression of apoC1 led to glomerulosclerosis, suggesting its involvement in diabetic nephropathy." (PMID 31779116, 2019). "Increased apoC1 levels were detected by proteomic analysis in cases of diabetic nephropathy in patients with type 1 diabetes, supporting the results of genetic association studies." (PMID 31779116, 2019). "The authors suggest that apoC1 might play a local role in the development of diabetic nephropathy, probably by increasing macrophage activation in renal tissue." (PMID 36471375, 2022). "Four of the peaks that were discovered have been identified as transthyretin, apolipoprotein A1, apolipoprotein C1 and cystatin C. Several yet unidentified proteins discovered by this novel approach appear to have more potential as biomarkers for diabetic nephropathy." (PMID 20205888, 2010). "In the clinical part of the same study, apoC1 was detected only in the kidneys from autopsied diabetic subjects and not in control subjects and the amount of apoC1 in glomeruli was significantly higher in patients with diabetic nephropathy than in those without diabetic nephropathy." (PMID 36471375, 2022).
clear cell renal cell carcinoma (8 papers, 2020 to 2023). "A study showed that APOC1 was highly expressed in clear cell renal cell carcinoma, and a variant of APOC1 called T45S led to elevated rates of T2D." (PMID 35399945, 2022). "Additionally, APOC1 represents a novel diagnostic marker for clear cell renal cell carcinoma and stimulates renal cell carcinoma through Wnt3a/STAT signaling." (PMID 37305534, 2023). "In clear cell renal carcinoma, APOC1 facilitates the activation of signal transducer and activator of transcription (STAT3) and promotes the metastasis of tumor cells." (PMID 37576389, 2023). "For example, APOC1 facilitates clear cell renal cell carcinoma metastasis by STAT3 pathway activation." (PMID 34298684, 2021). "Recent research also has identified ApoC1 which promotes renal clear cell carcinoma metastasis through activation of the STAT3 pathway and is a potential novel diagnostic and prognostic marker for clear cell renal carcinoma." (PMID 36891052, 2023). "APOC1 expressed at relatively high levels is a negative prognostic indicator and correlates with poor overall survival for patients with clear cell renal cell carcinoma." (PMID 34298684, 2021).
renal cell carcinoma (8 papers, 2021 to 2025). "TAMs with the M2 phenotype are produced when renal cell cancer cells are cocultured; this is prevented by silencing APOC1." (PMID 36908705, 2023). "Additionally, through secreting CCL5, macrophages overexpressing APOC1 aided in the spread of renal cell cancer cells." (PMID 36908705, 2023). "Moreover, apolipoprotein C1 promoted Wnt3a to stimulate progression of renal cell carcinoma." (PMID 34781823, 2021).